ALK (ALK receptor tyrosine kinase)
Diseases named in the same sentence as ALK in open-access papers (continued):
Sharing a sentence is not in itself a finding about the gene and the disease.
breast carcinoma (continued). "There is a wide variation in overexpression of ALK that has been reported in different subtypes of breast cancer." (PMID 26384210, 2015). "Based on these findings, a potential role for an ALK inhibitor, as a therapeutic agent targeting aggressive subtypes of breast cancer, merits further investigation." (PMID 26384210, 2015). "The purpose of this study was to determine the incidence and frequency of ALK amplification and rearrangements in different breast cancer subtypes including triple negative and inflammatory breast cancers." (PMID 26312204, 2015). "Our study is one of the largest clinical studies to have investigated ALK gene rearrangements and amplification in breast cancer and the only study to include all subtypes." (PMID 26312204, 2015). "Of the 1009 breast cancer cases investigated, 36.0 % (350/972) of cases showed positive staining of ALK by IHC." (PMID 26384210, 2015). "This study is one of the largest studies to have investigated ALK aberrations in breast cancer and the only study to include all subtypes." (PMID 26312204, 2015). "In conclusion, we have comprehensively investigated the ALK alterations in a large cohort of breast cancer cases." (PMID 26384210, 2015). "The Cancer Genome Atlas (TCGA) dataset has also shown ALK amplification in 9 % of the breast cancer cases." (PMID 26384210, 2015). "It has been demonstrated that inhibition of ALK inhibits growth of breast cancer cell lines and also tumor xenografts in mouse models." (PMID 26384210, 2015). "Although statistical significance was not reached probably due to the small sample size, this result suggests that ALK CNG is common in TNBC among four subtypes of breast cancer." (PMID 25803816, 2015). "A few recent studies have investigated the role of ALK aberrations in breast cancer, particularly in the context of inflammatory breast cancer and triple negative breast cancers, however, the results have been conflicting." (PMID 26312204, 2015). "We observed extra copy numbers of ALK as a result of chromosome 2 polysomy in 62 % of breast cancer cases." (PMID 26312204, 2015). "This study highlights that copy number gain of ALK gene is the result of polysomy of chromosome 2 and reflects a common phenomenon in all breast cancer subtypes, specifically in inflammatory and ER−/PR−/HER2+ breast cancers." (PMID 26312204, 2015). "We further correlated ALK alterations with clinical data including survival analysis, pathological parameters and other molecular markers in breast cancer patients." (PMID 26384210, 2015). "We aimed to comprehensively study the prevalence of ALK expression, and changes in copy number and translocation in a large cohort of breast cancer cases in a Middle Eastern population." (PMID 26384210, 2015). "Immunohistochemical analysis showed ALK is overexpressed in a substantial proportion of breast cancers and possibly plays a significant role in the aggressive behavior of this cancer." (PMID 26384210, 2015). "There are very few studies exploring ALK gene aberrations in breast cancer, and the results yielded have been conflicting." (PMID 26312204, 2015). "Immunohistochemical analysis showed ALK overexpression in 36.0 % of the breast cancer patients and gene amplification was present in 13.3 % of cases, seen by FISH analyses." (PMID 26384210, 2015). "Our goal was to determine the incidence of ALK aberrations in relation to different breast cancer types." (PMID 26312204, 2015). "Collectively, these observations suggest that EML4-ALK abnormalities are likely relatively rare in breast cancers in general, with ALK gene expression and activation of the ALK signaling pathway more common in TNBC." (PMID 24102046, 2013). "Recent studies reported that receptor tyrosine kinases (RTKs) such as c-Met and ALK contributed to PARPi resistance, and combined inhibition of these RTKs with PARPi induced synthetic lethality in breast cancer, liver cancer, pancreatic cancer, and ovarian cancer." (PMID 37883181, 2024).
breast carcinoma (continued). "These alterations were detected in 9 NSCLC samples (2 ALK rearrangements and 5 EGFR mutations, 1 BRAF mutation, and 1 G12C/KRAS mutation); 7 breast cancer samples (7 HER2 amplifications); 5 colon cancer samples (5 KRAS mutations); and 3 gastric cancer samples (2 MSI-high and 1 HER2 amplification)." (PMID 36832270, 2023). "If these studies find the drug to be tolerable, it would be highly interesting to extend the approach to clinical studies that combine SHP2 inhibitors with PI3K, MEK, BRAF or ALK inhibitors in breast cancer and further types of tumors which exhibit aberrations in the associated pathways." (PMID 35365185, 2022). "Collectively, SY-707 could be developed as a multiple drug candidate for multiple indications including breast cancer besides ALK-positive NSCLC." (PMID 35538024, 2022). "The dual MET/ALK inhibitor crizotinib showed a dose-dependent reduction of viability in various breast cancer cell lines after 48 h of treatment, with an IC50 of 5–10 μM18, which is similar to the IC50 obtained in our HGF-stimulated, crizotinib-treated chordoma cells." (PMID 34127734, 2021). "Therefore, we aimed in our study to assess ALK expression by immunohistochemistry in different types of breast cancer using 2 different ALK antibody clones." (PMID 31393373, 2019). "Moreover data generated from The Cancer Genome Atlas (TCGA) database on 479 breast cancer cases has also confirmed ALK deletions and copy number variations in breast tumors." (PMID 26384210, 2015). "Therefore, identification of aberrations in genes such as ALK will be clinically useful for breast cancers, given the availability of various ALK inhibitors." (PMID 26312204, 2015). "ALK protein expression was investigated by immunohistochemistry and numerical and structural variations of the ALK gene were analyzed by fluorescence in situ hybridization (FISH) in a tissue microarray format in a cohort of more than 1000 Middle Eastern breast cancers." (PMID 26384210, 2015). "It would be of interest to study whether ALK tyrosine kinase inhibitors would be effective in breast cancers with ALK copy number gains." (PMID 26312204, 2015). "In this study, ALK overexpression was seen in 36 % of Middle Eastern breast cancer cases and this observation is in concordance with an earlier published study showing 47 % of ALK overexpression in a cohort of 100 breast cancer cases." (PMID 26384210, 2015). "ALK amplification was seen in 13.3 % of our breast cancer cohort." (PMID 26384210, 2015). "Indeed, patients with HER2-positive breast cancer respond to trastuzumab, lapatinib, and pertuzumab, and ALK-rearranged advanced lung tumors respond to the ALK inhibitor crizotinib." (PMID 24811890, 2014). "Very few studies have investigated the status of the ALK gene in breast cancer." (PMID 24156086, 2013). "Key molecular determinants include EGFR/ALK alterations in NSCLC-derived metastases and HER2 status in breast cancer, which modulate BBB permeability and residual micrometastatic burden." (PMID 40722321, 2025). "Among them, advanced HER2+ breast cancer had the highest annual average treatment cost (USD 67,685), followed by ALK and ROS1 NSCLC at USD 65,316 and USD 46,176, respectively." (PMID 40740130, 2025). "Certain targets were enriched in specific cancer types as expected based on the clinical treatment landscape or tumor biology (eg, EGFR, MET, ROS1, MET, and ALK in NSCLC; or ERBB2, CDK4, CDK6, aromatase, and ER in breast cancer)." (PMID 37682776, 2024). "This case report provides evidence that the concurrent use of Alectinib, Trastuzumab, and Pertuzumab can be an effective treatment for patients with overlapping ALK-rearranged NSCLC and HER2-mutant breast cancer." (PMID 37113357, 2023). "In both ovarian and breast cancer PARP inhibitor-resistant xenograft models, mice treated with the combination of PARP and ALK inhibitors demonstrated improved survival compared with mice treated with monotherapy." (PMID 36253486, 2022).
breast carcinoma (continued). "Eventually, researchers have discovered a direct relationship between ALK and cyclin-dependent kinase 9 (CDK9) in breast cancer, where ALK phosphorylates CDK9, leading to resistance against Poly(ADP-Ribose) Polymerase (PARP) inhibitors and encouraging homologous recombination repair." (PMID 38397899, 2024). "In breast cancers, the most prevalent fusion genes were FGFR family genes (total, 0.48%; FGFR2, 0.34%; FGFR1, 0.14%), ErbB family genes (total, 0.47%; EGFR, 0.20%; ERBB2, 0.27%), ALK (0.27%) and ROS1 (0.07%)." (PMID 36369474, 2022). "We, therefore, believe that studies on the expression of both ALK and CD30 in breast carcinoma are still necessary, given the potential benefit of targeted therapy on breast cancers with aggressive biology and poor response to conventional chemotherapeutic regimens." (PMID 31393373, 2019). "The PTN-RPTPβ/ζ pathway has been also reported to affect phosphorylation and/or activation of numerous targets, such as ALK, Fyn and its downstream substrate beta catenin, protein kinase C (PKC) alpha or beta through inhibition of the phosphatase activity in breast cancer." (PMID 30427932, 2018). "The critical fault of IGF1R inhibitor is the lack of a predictive biomarker such as ERBB2-positive breast cancer for trastuzumab or ALK-fusion protein-driven NSCLC for crizotinib." (PMID 30404198, 2018). "Due to its ability to act as a molecular chaperone that can stabilize many onco-proteins, HSP90 has been reported as a druggable target in many cancers, including ALK-rearranged NSCLC, HER2-amplified breast cancer and some hematological malignancies (e.g., multiple myeloma)." (PMID 28290473, 2017). "ALK inhibitors alone or in combination can be exploited as a novel therapeutic agent in aggressive subtypes of breast cancers." (PMID 26384210, 2015). "Neither ALK gene rearrangements nor amplification were identified in the 133 breast cancer cases evaluated in our study." (PMID 26312204, 2015). "Neither ALK rearrangements nor amplification were identified in the 133 breast cancer cases evaluated." (PMID 26312204, 2015). "Our study demonstrated that ALK gene was neither rearranged nor amplified in any of the 133-breast cancer cases evaluated by FISH." (PMID 26312204, 2015). "Since TNBC is a poor prognosis breast cancer lacking any molecular target, so ALK overexpression can be exploited as a possible therapeutic target." (PMID 26384210, 2015). "Thus we attempted to investigate the structural and numerical alterations of ALK by fluorescence in situ hybridization (FISH) and protein expression by immunohistochemistry (IHC) in a large cohort of Middle Eastern breast cancers." (PMID 26384210, 2015). "We believe that ALK testing algorithm defining positive, equivocal, and negative values might be recommended as the guideline for HER2 testing in breast cancer." (PMID 24667320, 2014). "Combined with the fact that PD-L1 expression would be induced by activated immune cells and inflammatory chemokines, we speculated that, similar to hepatocellular carcinoma and breast cancer above, the intratumoral TLS of ALK+ tumors were more activated than peritumoral TLS." (PMID 36233802, 2022). "In addition, we also did not observe any ALK gene amplification in six breast cancer cell lines (Cal-120, EFM-19, HDQ-PI, CAL-51, MT-3, and MCF-10) analyzed, however, two cell lines (HCC-1937 and MDA-MB231) showed amplification of the ALK gene." (PMID 26384210, 2015). "Previous studies did not observe ALK rearrangement in breast cancer patients." (PMID 25803816, 2015). "ALK alterations such as increased ALK copy number, gene amplification and translocation have been shown to be present in 80 % of inflammatory breast cancer and 25 % of triple-negative breast cancers (TNBC), which are considered to be the most aggressive subtypes of breast cancers." (PMID 26384210, 2015).
breast carcinoma (continued). "In summary, we showed the lack of ALK and CD30 immunoreactivity in breast cancer in our cohort, irrespective of tumor characteristics." (PMID 31393373, 2019).
squamous cell carcinoma (100 papers, 2010 to 2025). A carcinoma arising from squamous epithelial cells. "In the squamous carcinoma group, the main mutations were ALK (Ile1461Val), in 100% of patients, and EML4 (Lys398Arg) in 75% of the patients." (PMID 36422072, 2022). "The ALK p.F921C mutation was reported in squamous cell carcinoma and adenocarcinoma and were predicted as pathogenic, while the ALK p.P1139L mutation was a novel variant with uncertain clinical significance." (PMID 35628499, 2022). "In our case, the postoperative pathology revealed that the squamous cell carcinoma suffered from ALK fusion mutation." (PMID 32727606, 2020). "The relationship between squamous cell carcinoma and ALK gene status (including rearrangement, mutation, and copy number gain) still needs to be elucidated." (PMID 32727606, 2020). "Real-time polymerase chain reaction (PCR) analysis showed that the adenocarcinoma had an epidermal growth factor receptor (EGFR) mutation presenting as point mutation L858R, while the squamous cell carcinoma suffered from ALK fusion." (PMID 32727606, 2020). "The present study revealed that although adenocarcinoma was the most common pathological type to be submitted for EGFR/ALK evaluation, patients with squamous carcinoma had an EGFR mutation rate of 8.3% and an ALK rearrangement rate of 3.7%." (PMID 31144459, 2019). "Taken together, this study emphasizes that EGFR mutation test for squamous cell carcinoma need to as well be considered as a routine practice, as recommended for ALK mutations with comparable incidence at around 5%." (PMID 24124538, 2013). "Although p63 positivity is often used as a marker of squamous cell carcinoma in diagnostic pathology, we found that a few ALK-rearranged tumors coexpressed p63 and TTF1 in the adenocarcinoma component." (PMID 23922677, 2013). "Additionally, specific subtypes are characterized by different mutations: adenocarcinoma typically exhibits changes in the EGFR and ALK genes, while squamous cell carcinoma is associated with alterations in the PIK3CA and FGFR1 genes." (PMID 38339175, 2024). "Wang reported that in addition to having a fusion rate lower than that in adenocarcinoma, squamous cell carcinoma may also have ALK gene copy number gain and ALK gene mutation." (PMID 32727606, 2020). "However, this is understandable, as the majority of EGFR mutations and ALK-positivity cases were found in adenocarcinomas, with an extremely low mutation rate in squamous cell carcinoma (< 5%)." (PMID 32690092, 2020). "Spatial proximity between bronchus and ALK-rearranged tumors and frequent solid histologic subtype with p63 expression may cause diagnostic difficulties to differentiate squamous cell carcinoma in the small biopsy, whereas p40 was rarely expressed in ALK-rearranged adenocarcinoma." (PMID 24194854, 2013). "In patients with squamous cell carcinoma, approximately 30% of tests for EGFR, ALK, and RET mutations were positive, which confirms the importance of testing at least a preselected subgroup of patients." (PMID 39518907, 2024). "According to earlier research, the percentage of ALK-positive squamous cell carcinoma cases discovered by PCR or IHC/FISH is as low as 1%." (PMID 39518064, 2024). "The parameters analyzed included histopathological type (NSCLC: squamous cell carcinoma or adenocarcinoma; SCLC), molecular mutations (EGFR, ALK, PD-L1), parameters from the complete blood count, inflammatory parameters, and associated comorbidities." (PMID 39199673, 2024). "Immunostaining revealed that the squamous cell carcinoma was ALK positive, suggesting a squamous transformation of the adenocarcinoma." (PMID 38829559, 2024). "Epithelial-to-mesenchymal transition (EMT) and small cell lung cancer (SCLC) or squamous cell carcinoma conversion have been reported after ALK inhibitor therapy for ALK-p adenocarcinoma." (PMID 36768562, 2023).
squamous cell carcinoma (continued). "All but one patient with stage III squamous cell carcinoma (SCC) were confirmed to have adenocarcinoma and tested for EGFR mutation and ALK rearrangement at diagnosis." (PMID 36434641, 2022). "In the case of adenocarcinoma (even in dimorphic combination with squamous cell carcinoma), a molecular genetic assay of EGFR mutations (18–21 exons), BRAF, V600E, ALK, and ROS1 is recommended." (PMID 35982978, 2022). "Detection of sensitive mutations in genes, such as EGFR, ALK, and ROS1, is required for advanced non-squamous cell carcinoma of NSCLC." (PMID 35029237, 2022). "ALK rearrangement should be tested in all patients with adenocarcinoma or non-squamous carcinoma, and also in squamous cell carcinoma in patients aged < 50 years of age and/or with low or no tobacco use." (PMID 34112097, 2021). "The lowest number of ALK rearrangments (0.7%) were observed in patients with a history of smoking and squamous cell carcinoma." (PMID 34786182, 2021). "ALK rearrangement is a very rare subset of squamous cell carcinoma (SCC) and one of the clinical features in patients is lack of data." (PMID 33565277, 2021). "The second specimen, collected later from a recurrent lesion in his right main bronchus, showed a squamous cell carcinoma and was positive for ALK rearrangement, as assessed by RNA-seq." (PMID 32674491, 2020). "In spite of the remarkable responses have been observed by some researchers, it is still controversy about the efficacy of ALK inhibitor in ALK-rearranged squamous cell carcinoma." (PMID 32727606, 2020). "NSCLC samples included 81 (17%) EGFR-positive, 37 (8%) ALK-positive, and 91 (19%) squamous-cell carcinoma specimens." (PMID 32127616, 2020). "Because of the relatively high mutation rate, patients with squamous cell carcinoma should also be routinely tested to determine their EGFR and ALK statuses." (PMID 31144459, 2019). "Among patients with squamous cell carcinoma, the EGFR mutation rate was 8.3% and the ALK rearrangement rate was 3.7%." (PMID 31144459, 2019). "Among patients with squamous cell carcinoma, the EGFR mutation rate was 8.3% (9/109) and the ALK rearrangement rate was 3.7% (4/109)." (PMID 31144459, 2019). "Herein, we report a case of squamous cell carcinoma (SCC) with ALK rearrangement treated with alectinib." (PMID 29744229, 2018). "An ALK rearrangement analysis was performed in 195 cases (140 adenocarcinomas, 50 squamous cell carcinomas, 3 adenosquamous carcinomas, 2 large-cell carcinomas)." (PMID 28704499, 2017). "In the non-squamous cell carcinoma subgroup, comprising in total 548 patients, the frequency of ALK positivity was 2.0 % (11 patients)." (PMID 27495736, 2016). "ALK rearrangements were detected in 1.7 % in the complete cohort and 2.0 % in the non-squamous cell carcinoma subgroup." (PMID 27495736, 2016). "Of the 44 patients with ALK rearrangement, 43 (97.7%) had adenocarcinomas, and 1 (2.3%) had squamous carcinoma." (PMID 26253541, 2015). "ALK expression was compared between different hyperproliferative skin diseases, such as psoriasis vulgaris and squamous cell carcinoma (SCC)." (PMID 24163262, 2013). "Notably, our cohort was predominantly squamous cell carcinoma, in which EGFR/ALK mutations are rare, minimizing their likely impact." (PMID 40623866, 2025). "Four patients with squamous cell carcinoma had molecular abnormalities atypical for this histological type, suggesting a secondary adenocarcinomatous contingent: a KRAS G12C mutation, a KRAS amplification, a STK11 mutation and an ALK mutation." (PMID 39764418, 2024). "Although these first- and new generation TKIs improved the survival for patients with non-squamous cell carcinoma and EGFR or ALK mutation, these patient populations accounted for a low percentage of the overall NSQ group (approx. 10% and 4% based on clinical references)." (PMID 37860193, 2023).